RNASE7 (ribonuclease A family member 7)
Diseases named in the same sentence as RNASE7 in open-access papers (continued):
Sharing a sentence is not in itself a finding about the gene and the disease.
infection (19 papers, 2013 to 2025). The state of being infected such as from the introduction of a foreign agent such as serum, vaccine, antigenic substance or organism. "RNase7, produced in keratinocytes, is involved in protecting the skin from infection caused by S. aureus and has antimicrobial activities against E. coli, P. aeruginosa, E. faecium, and P. acnes." (PMID 40284707, 2025). "As we continue to evaluate RNase 7’s contributions to host defense, we will begin to understand if dysregulation of RNase 7 production affects infection susceptibility." (PMID 27011175, 2016). "Nevertheless, these initial studies give rise to the hypothesis that RNase 7 may play a role in infections caused by mycobacteria." (PMID 31749808, 2019). "Furthermore, infection of airway epithelial cells with Mycobacterium tuberculosis led to induction of RNase 7 expression and an intracellular association of RNase 7 with Mycobacterium tuberculosis." (PMID 31749808, 2019). "To date, it is unknown whether deficient RNase 7 production increases infection risk or if increased RNase 7 production shields the host from microbial challenge." (PMID 27011175, 2016). "The production of antimicrobial peptides and proteins (AMPs) such as RNase 7 may explain why the skin at the perianal region is highly resistant to infection caused by Enterococci despite the permanent contact with these abundant gut bacteria." (PMID 27089327, 2016). "Thus, one may hypothesize that a reduced RNase 7 expression may contribute to the increased infection risk in patients receiving anti-EGFR therapy." (PMID 27089327, 2016). "Similar to the other AMPs, infection of the skin models in this study resulted in a significant increase in RNASE7 gene expression." (PMID 37237836, 2023). "RNase7 has broad-spectrum antimicrobial activity against uropathogenic bacteria, and its expression increases during an infection." (PMID 37759520, 2023). "Psoriasin and RNase 7 concentrations increase over time on the skin of newborn infants and seem to play a role in the first defense against infection." (PMID 36923410, 2023). "The downregulation of RNase 7 can make the skin of DM2 patients prone to infection and affect the healing of ulcer wounds." (PMID 35563546, 2022). "The colony assay also revealed that the infection rate of the pretreated 25 μg/mL RNase 7 group was even lower than that of the UPEC infection control group (p < 0.01)." (PMID 35563546, 2022). "While some of these peptides, including RNase 4 and RNase 7, are abundantly produced by epithelial cells, the expression of others, like RNase 3 and RNase 6, increase at infection sites with immune cell recruitment." (PMID 31849967, 2019). "If individuals with recurrent infections or increased infection risk have suppressed RNase 7 activity, it is possible that this could occur secondary to genetic variation, deficient protein production/function, or the ability of pathogens to directly suppress RNase 7 production." (PMID 27011175, 2016). "For example Spencer and colleagues observed high expression of RNase 7 in the urinary tract and they demonstrated an important role of RNase 7 to protect the urinary tract from infection." (PMID 27089327, 2016). "The finding that RNase 7 expression is mainly located in the outermost layers of human skin correlates with the supposed function of RNase 7 to protect human skin from infection." (PMID 27089327, 2016). "Additionally, expression of antimicrobial RNase 7 by basal cells was observed after experimental infection of human bronchial epithelial cells with the respiratory pathogen nontypeable Haemophilus influenzae." (PMID 36902418, 2023). "The increase in CAMP and RNASE7 mRNA levels during infection of metformin treated uroepithelial cells could be attributed to rapid transcriptional activation." (PMID 34584119, 2021). "Similarly, RNase7 protein expression also increased in 5637 cells upon infection, though only mRNA upregulation was observed in TERT-NHUC." (PMID 34584119, 2021).
infection (continued). "Keratinocyte infection with DENV was also shown to induce RNase 7 gene expression." (PMID 32582097, 2020). "In addition, the influence of immunomodulatory activities as well as the interaction of RNase 7 with the microbiota have to be considered when using RNase 7 in the treatment or prophylaxis of infections." (PMID 31749808, 2019). "In addition, the stimulation of keratinocytes with RNase 7 and DNA induced an interferon-beta (IFNß) dependent antiviral response which was sufficient to counteract an infection of the keratinocytes with herpes-simplex virus 1 (HSV-1)." (PMID 31749808, 2019). "Several studies point to a relevance of RNase 7 in protecting healthy skin from infection." (PMID 27089327, 2016). "Therefore, Spencer and colleagues analyzed the relevance of RNase 7 to protect the urinary tract from infection with uropathogenic bacteria." (PMID 27089327, 2016). "Interestingly, the inductions of hBD-3 and RNase 7 by S. epidermidis highlight a possible mechanism of how skin commensals, such as S. epidermidis, amplify the innate immune response in the presence of infection." (PMID 40284707, 2025). "Indeed, there is increasing evidence that RNase 7 may play an important role to protect skin from infection." (PMID 31749808, 2019). "RNase 7 is secreted into the urine and urinary concentrations increase with UTI to prevent infection." (PMID 31849967, 2019). "Its capacity to negatively regulate at least two different types of innate defense gene, RNase7 and ST2, suggests a role in regulation of ocular innate defense in response to infection that might also occur at other mucosal surfaces." (PMID 23469087, 2013). "RNase 7 expression was not influenced by infection with C. albicans." (PMID 29736603, 2018). "In addition, when compared to co-incubation with the inhibitor alone, the infection rate of either JAK1 or STAT1 inhibitor treatment was significantly higher without RNase 7 pretreatment (p < 0.01, compared to AMP plus JAK1 or STAT1 inhibitor treatment, respectively)." (PMID 35563546, 2022). "Median values of hBD-2 (V = 90, P < 0.001), RNase 7 (V = 286, P > 0.05), IL-1β (V = 749, P > 0.05) and IL-8 (CXCL-8) (V = 413, P < 0.001) increased during infection, but not for IL-6." (PMID 36382385, 2022).
tumor (5 papers, 2010 to 2024). "CXCL5, ELN, JUN, and FGFR4 were highly expressed in normal tissues, while PLAU, RNASE7, JAG1, SPP1, and TNFRSF18 were highly expressed in tumor tissues." (PMID 32699529, 2020). "Moreover, in terms of PIK3R3, RNASE7, and TNFRSF12A, similar results have been obtained in other researches, indicating that these genes might be engaged in immune-related pathways and promote tumor progression." (PMID 33193693, 2020).
cancer (3 papers, 2017 to 2023). A tumor composed of atypical neoplastic, often pleomorphic cells that invade other tissues. "A failure to adequately induce RNase 7 may contribute to the increased cutaneous infection risk of cancer patients receiving anti-EGFR therapy." (PMID 29066761, 2017). "Although RNASE7, encoding an antimicrobial peptide, was not demonstrated to be associated with CRC, the roles of itself and its family members in other cancers may indirectly verify our conclusions." (PMID 33833937, 2021).
infectious disease (3 papers, 2009 to 2016). A disorder directly resulting from the presence and activity of a microbial, viral, or parasitic agent in humans. "It is likely that a dysregulation of RNase 7 may be associated with cutaneous inflammatory and infectious diseases." (PMID 27089327, 2016). "An interesting speculation is that dysregulation of RNase 7 may result in higher susceptibility to infectious diseases." (PMID 19641608, 2009). "In doing so, we conclude by highlighting key knowledge gaps that must be investigated to completely understand the potential of developing RNase 7 as a novel therapeutic for human infectious diseases." (PMID 27011175, 2016).
bacterial infection (2 papers, 2017 to 2025). "Considering that RNase6 and RNase 7 expression is induced in macrophages upon bacterial infection, one might hypothesize that these antimicrobial proteins can also play a physiological role against intracellular dwelling mycobacteria." (PMID 29163551, 2017). "Despite the absence of a murine RNASE7 orthologue, humanised RNase 7 transgenic mice enabled the demonstration that this antimicrobial protein can protect the urinary tract from bacterial infection." (PMID 41230022, 2025).
RNASE7 also shares sentences with these, for which no sentence is quoted: actinic keratosis (1 paper); breast carcinoma (1); chorioamnionitis (1); cutaneous squamous cell carcinoma (1); E. coli infections (1); eczema herpeticum (1); hepatocellular carcinoma (1); ichthyosis (1); keratitis (1); lymph node metastasis (1); oral squamous cell carcinoma (1); pancreatic cancer (1); pityriasis versicolor (1); type 2 diabetes (1).